NAGS (N-acetylglutamate synthase)
Diseases named in the same sentence as NAGS in open-access papers (continued):
Sharing a sentence is not in itself a finding about the gene and the disease.
lysinuric protein intolerance (1 paper, 2018). Lysinuric protein intolerance (LPI) is a very rare inherited multisystem condition caused by disturbance in amino acid metabolism. "Deficiencies of arginase, N-acetylglutamate synthase, carbamoyl phosphate synthetase, citrin, and lysinuric protein intolerance were also observed." (PMID 30285816, 2018).
orotic aciduria (1 paper, 2023). An extremely rare autosomal recessive inherited disorder caused by mutations in the UMPS gene. "Similarly, orotic acid in urine is a biomarker of the following metabolic diseases: Ornithine Transcarbamylase Deficiency, N-Acetylglutamate Synthase Deficiency, and Orotic Aciduria." (PMID 37627634, 2023).
stomach adenocarcinoma (1 paper, 2023). "The CNV of NAGS and CPS1 were similar in stomach adenocarcinoma samples." (PMID 37047726, 2023).
genetic diseases (2 papers, 2023 to 2025). "There was little overlap between somatic sequence variants found in tumor samples and germline sequence variants found in patients with NAGS, CPS1, and citrin deficiencies, and in individuals without rare genetic diseases." (PMID 37047726, 2023). "There was little overlap between NAGS, CPS1, and citrin sequence variants found in patients with respective deficiencies, tumor samples, and individuals without known rare genetic diseases." (PMID 37047726, 2023). "NAGS, CPS1, and citrin sequence variants present in individuals without rare genetic disorders were collected from the gnomAD database." (PMID 37047726, 2023).
tumor (2 papers, 2019 to 2023). "NAGS, CPS1, and citrin sequence variants found in tumor samples were collected from the TCGA, COSMIC, and cBioPortal databases of tumor genomic information." (PMID 37047726, 2023). "We queried repositories of tumor genomic data to determine whether the higher expression of NAGS, CPS1, and citrin genes correlate with unfavorable patient outcomes." (PMID 37047726, 2023). "The correlation between NAGS and CPS1, citrin and NAGS, and CPS1 and citrin mRNA expression in individual tumor samples was either weak or negligible." (PMID 37047726, 2023). "Therefore, we compared the types of NAGS, CPS1, and citrin sequence variants found in all tumor samples with sequence variants found in individuals without known rare diseases, and patients with NAGS, CPS1, or citrin deficiencies to increase the power of comparison." (PMID 37047726, 2023). "This study used data mining to assess whether the aberrant expression of NAGS and biosynthesis of NAG can explain the increased activity of CPS1 that contributes to higher de novo pyrimidine production and tumor cell proliferation." (PMID 37047726, 2023). "Despite the lack of efficacy in this setting, vaccine-induced nAgs-specific T cells were recovered from tumor infiltrates 10 days post vaccination and their effector function was measured ex vivo after re-stimulation with cognate nAgs peptides showing an effective production of IFN-γ by ICS assay." (PMID 31217437, 2019).
NAGS also shares sentences with these, for which no sentence is quoted: citrullinemia (3 papers); arginase deficiency (2); argininosuccinic aciduria (2); cancer (2); Hyperornithinemia (2); metabolic disease (2); cystic fibrosis (1); esophageal cancer (1); Fabry disease (1); Gaucher disease (1); glioma (1); Hepatic fibrosis (1); hepatoma (1); hereditary angioedema (1); Hunter syndrome (1); Hyperphenylalaninemia (1); infection (1); LCHAD deficiency (1); liver cancer (1); melanoma (1); methylmalonic acidemia (1); mucopolysaccharidosis (1); myelofibrosis (1); Ornithine transcarbamylase deficiency (1); propionic acidemia (1); Sepsis (1); tyrosinemia (1).